INS (insulin)
Diseases named in the same sentence as INS in open-access papers (continued):
Sharing a sentence is not in itself a finding about the gene and the disease.
diabetes (continued). "In Asian populations, diabetes screenings are recommended to begin at lower BMI’s than in other ethnicities (23 vs 25 kg/m2), due to differences in body composition (higher amount of visceral fat), higher insulin resistance, and lower second phase insulin secretion." (PMID 29780358, 2018). "Diabetes mellitus (DM) is a metabolic disorder of multiple etiologies that is characterized by chronic hyperglycaemia due to impairments in insulin release, insulin actions or both." (PMID 30459707, 2018). "However, more than 25% of patients in the United States with diabetes take insulin." (PMID 29555621, 2018). "Diabetes Canada states that metformin may be used as an alternative to insulin adding that women should be informed that metformin crosses the placenta, longer term studies are not yet available and the addition of insulin is necessary in approximately 40% to achieve adequate glycaemic control." (PMID 29973490, 2018). "Although associations between diabetes and fungicides have never been reported in any epidemiological study prior to this, a recent tissue-culture study reported that fungicide exposure can cause insulin resistance in fat cells and causes higher blood glucose." (PMID 29374457, 2018). "In addition, one could predict that islet preparations with a low number of “responder islets” and a high number of “dormant islets” would be less likely to efficiently sustain insulin production after their transplantation into subjects with diabetes." (PMID 30098928, 2018). "Furthermore, many other factors, such as the nutritional/metabolic status and endogenous insulin levels of the patients, which are interrelated with the severity of diabetes and diabetes treatment, might influence mTOR signaling." (PMID 29486734, 2018). "However, exogenous injections of insulin did not reverse the decreased Kiss1 gene expression, which was induced by fasting- and diabetes-associated metabolic perturbations." (PMID 29643834, 2018). "One study with 169 patients infected with CHIKV showed that the presence of diabetes has worsened the severity of symptoms and changes in glycemic state resulting in necessary adjustments for medications in approximately 40% of the cases, even in those with insulin treated patients." (PMID 29686737, 2018). "Furthermore, only a very small number of CHI patients with diabetes are treated with insulin pumps." (PMID 30577875, 2018). "A series of univariate tests were run to determine which factors may account for variance in HbA1c including sex, age, insulin regimen, BMI z-score, insulin rate per kg, duration of diabetes, ACARFS score, percent of diet from protein/carbohydrate/fats/saturated fats and from ‘core foods’." (PMID 29549246, 2018). "In this study, we found that p66Shc signaling contributes to cognitive decline in high blood glucose model (STZ-induced diabetic mice) and further investigation is required for whether this is applicable to all type of diabetes such as high fat-induced insulin resistant state." (PMID 29453337, 2018). "Multivariate analysis identified diabetes duration, HbA1c, triglyceride and low HDL-C values, presence of retinopathy or renal dysfunction, and sulphonylurea utilization (the risk being approximately 3 times greater in the latter case) as independent predictors of insulin treatment initiation." (PMID 30327785, 2018). "Furthermore, changes in the corneal epithelial, stromal, and neuronal cell populations during diabetes occurs during chronic exposure to high glucose with significant fluctuations in hormone levels, such as insulin, that influence the global response to elevated glucose levels." (PMID 30470798, 2018). "In addition, it has been shown in mice that ZnT8 expression is downregulated in the early stages of diabetes, suggesting that many patients with hyperglycemia may suffer from dysregulated insulin clearance." (PMID 29791512, 2018).
diabetes (continued). "Dispelling the idea that insulin use is an indicator of current diabetes control and addressing beliefs regarding the number of medications taken could shift patients’ perceptions regarding diabetes control." (PMID 30400859, 2018). "Diabetes mellitus (DM) comprises a heterogeneous group of metabolic disorders that commonly feature hyperglycemia, which results from disturbances in insulin secretion, insulin action, or both." (PMID 29791661, 2018). "In addition to fish, insulin resistance in hibernating bears, dolphins, horses, bonnet macaques and chimpanzees demonstrate that the relationship between diet, obesity, insulin sensitivity and diabetes is widely different in different species." (PMID 30151194, 2018). "Furthermore, and despite the mechanistical evidence linking fetuin-A and insulin sensitivity, causal link of circulating fetuin-A with diabetes was not supported by a recent large Mendelian study in the general population." (PMID 30579336, 2018). "Moreover, RvD1 decreases adipose tissue macrophage accumulation and improves insulin sensitivity in obese-diabetic mice, suggesting that RvD1 could provide a novel therapeutic strategy for treating obesity-induced diabetes." (PMID 30618774, 2018). "Menopause seemed to modify the association between insulin and IGF1R expression (p = 0.07) and the difference in IGF1R expression between tumors of insulin and non-insulin users was only observed among premenopausal women with diabetes (OR = 5.10; 95%CI:1.36–19.14; p = 0.02)." (PMID 29486734, 2018). "Imperfect intensive insulin treatment may also reduce the warning symptoms and hormonal defenses against hypoglycemia leading to defective counterregulation and hypoglycemia unawareness; thus, intensive treatment may trigger severe hypoglycemia." (PMID 32232090, 2018). "Diabetes mellitus (DM), a metabolic dysfunction, is induced by defects in the secretion and action of insulin, a hormone that regulates the blood sugar level in the human body." (PMID 30103419, 2018). "Diabetes promotes the secretion and expression of Par-4, increases nuclear Par-4 levels in islet β cells, and inhibits Akt phosphorylation, consequently promoting islet β cell apoptosis and reducing islet β cell survival and glucose-stimulated insulin secretion." (PMID 30186877, 2018). "Moreover the coexistence of eating disorders and diabetes is frequently associated with non-compliance with treatment for diabetes and the abuse of insulin to promote weight reduction." (PMID 29744106, 2018). "The results show that artemether has beneficial effects on glucose homeostasis, insulin resistance, pancreas and liver architecture, the apoptosis of beta cells, and insulin secretion in db/db mice, which suggests that artemisinins may be useful in type 2 diabetes mellitus." (PMID 29862294, 2018). "Previously reported diabetes-specific features of anxiety include fear of complications, fear of hypoglycemia, and invasive self-care behaviors such as fear of injections, self-monitoring of blood glucose, and insertion of subcutaneous insulin infusion devices such as an insulin pump." (PMID 30214804, 2018). "Thus, the search for agents that may promote insulin sensitivity and β-cell survival may provide a more effective strategy to prevent the onset of diabetes." (PMID 29614722, 2018). "In addition to the direct effects of insulin on the brain, diabetes may also impact the brain through modulation of the inflammatory system." (PMID 30054579, 2018). "Notably, IL-1, which is a major proinflammatory cytokine, is present at increased levels in patients with diabetes mellitus, and could promote β-cell destruction and alter insulin sensitivity." (PMID 30598026, 2018). "Future studies will address whether Hes3 is also regulated in diabetes patients, which parameters of insulin deregulation and/or diabetes mellitus are primarily responsible for Hes3 regulation, and the roles that Hes3 plays in the progression of diabetes-related phenotypes." (PMID 30054579, 2018).
diabetes (continued). "However, a recent study has suggested that higher HbA1c, higher BMI and longer duration of diabetes at the time of transfer to SU therapy from insulin, may predict failure of SU monotherapy, making the case for early genetic diagnosis." (PMID 30377832, 2018). "This suggests that a change in peripheral insulin resistance may not be the major cause of acute diabetes remission and that the mechanism underlying diabetes remission may be at the level of the pancreas." (PMID 30687230, 2018). "This study aimed to determine whether l-arginine supplementation lasting for 18 months maintained long-lasting effects on diabetes incidence, insulin secretion and sensitivity, oxidative stress, and endothelial function during 108 months among subjects at high risk of developing type 2 diabetes." (PMID 29052766, 2018). "Moreover, insulin levels in obese rats are higher than those in lean rats, and postprandial hyperglycaemia has been reported to be a predictor of diabetes, which suggests an increased predisposition of CHSD rats to obesity or a decreased sensitivity to insulin." (PMID 30115853, 2018). "BMI had the most profound effect on insulin secretion in men and on IR in women in this 60-year-old cohort, suggesting that lifestyle modifications for obesity reduction in women remain the most important method for improving glucose metabolism and preventing future type 2 diabetes mellitus." (PMID 29377927, 2018). "Given its fundamental role in glucose metabolism, any defects on insulin secretion, action or both, will lead to a cluster of metabolic alterations characterized by chronic hyperglycemia known as diabetes mellitus (DM)." (PMID 29670917, 2018). "Furthermore, effects in people with diabetes might implicate insulin-related metabolic pathways and growth factors, or effects on extra-platelet COX." (PMID 30017552, 2018). "Finally, the inclusion of a patient treated with insulin for his diabetes may have introduced a confounding effect on sodium handling." (PMID 29876358, 2018). "Diabetes mellitus (DM) is a group of metabolic disorders characterised by a hyperglycaemic condition resulting from defects in insulin secretion, insulin action, or both." (PMID 29713364, 2018). "Two types of diabetes are common among humans: type 1 diabetes that occurs when the immune system attacks and destroys insulin and type 2 diabetes, the most common form, that may be caused by several factors, the most important being lifestyle, but also may be determined by different genes." (PMID 29507651, 2018). "The collection of multiple studies in animals and humans strongly supports the hypothesis that cigarette smoking and exposure to nicotine can adversely affect insulin action and the function of pancreatic cells, both of which play fundamental roles in the pathogenesis of diabetes." (PMID 30383737, 2018). "Although not a causal relationship, given that effective diabetes management includes insulin dosing, frequent blood glucose (BG) checking appears to be related to global self-care behavior, signifying that those who monitor BG more frequently are more likely to engage in good self-care." (PMID 30291085, 2018). "Furthermore, we found that after six weeks of intervention, mice treated with ketogenic diet and ketogenic diet combined with aerobic exercise both have lower body weights, HbAlc level, HOMA index, and higher insulin sensitivity, compared with diabetes control group." (PMID 29743883, 2018). "Methods and Results.The patient is a smoker and an occasional drinker, known with type two diabetes mellitus (DM), receiving insulin therapy." (PMID 29696066, 2018). "This study verifies that using a gelatin/CMC MN patch for insulin delivery achieves satisfactory relative bioavailability compared to a traditional hypodermic injection and can be a promising delivery device for poorly permeable protein drugs such as those used to treat diabetes." (PMID 30189671, 2018).
diabetes (continued). "Moreover, the finding of decreased expression of the pyruvate carboxylase enzyme may be because the model of diabetes we used begins to lower insulin levels after 16 weeks of age." (PMID 29857581, 2018). "Diabetes mellitus (DM) is defined as a group of metabolic diseases characterized by hyperglycemia that results from defects in insulin secretion, insulin action, or both." (PMID 29862283, 2018). "First, we assessed associations of insulin therapy with MD by comparing insulin-treated type 1 (T1D) and type 2 (T2D) diabetes patients with age-matched individuals without diabetes, overall and stratified by duration of insulin treatment and insulin glargine use." (PMID 30092829, 2018). "These diabetics represent around 10% of all diabetic patients, and in most cases, their condition is due to the death of pancreatic Langerhans islets ß-type cells, which normally secrete insulin to clear elevated glucose levels from the bloodstream, like after a meal." (PMID 29854726, 2018). "Visiting DM-specific social networking sites influenced more positive diabetes care behaviors, such as adhering to diet and exercise, glucose monitoring and insulin use." (PMID 30112191, 2018). "Accumulating evidence supports that miRNAs play a crucial role in the regulation of pancreatic β-cell function under normal and pathophysiological conditions, such as insulin biosynthesis, insulin exocytosis, and β-cell expansion, and may have clinical significance in diabetes." (PMID 30469437, 2018). "Longer duration of diabetes and insulin therapy may predict diabetic retinopathy." (PMID 30367589, 2018). "Interestingly, despite this increased energy and macronutrient intake, patients in the higher fiber intake group also had lower BMI, superior metabolic control of diabetes, and inferior use of medications to treat diabetes (insulin) and hypertension (ACE inhibitors)." (PMID 29694634, 2018). "Although the conventional glucose-lowering therapies such as metformin and insulin are widely prescribed for the treatment of diabetes, they may not be sufficient to limit the associated cardiovascular complications caused by hyperglycemia." (PMID 29867503, 2018). "Also, previous studies showed an association between small LDL particle size and insulin resistance as well as incident diabetes, although the association with diabetes was not independent after adjusting for insulin sensitivity or triglycerides." (PMID 29321013, 2018). "Diabetes mellitus (DM) is commonly derived from the defects in insulin secretion or insulin action, or both of them and the chronic DM would induce the damage or dysfunction of several organs, such as heart, eyes, nerves, as well as kidney and blood vessels." (PMID 29534728, 2018). "A potential explanation for the association between insulin therapy and NAF may be that DM on insulin are those with longer duration of diabetes, poor control of diabetes on oral agents prior to going on to insulin and also having significant other comorbidities." (PMID 30161122, 2018). "Diabetes mellitus (DM) is a chronic condition that occurs when the body cannot produce or effectively utilize insulin, which results in increased levels of glucose in the blood stream (hyperglycaemia) causing metabolic disorders of many organs over time." (PMID 30383776, 2018). "HCP explanations for low insulin adherence included: being too busy; travelling; the timing of meals; stress or emotional problems; public embarrassment; and the patient’s perception of their diabetes control:“....so it depends how their [patients’] lifestyle..." (PMID 29788908, 2018). "When insulin therapy is required, most elderly patients with advanced diabetes complications, life-limiting coexisting chronic illnesses, or limited functional status, once-daily basal insulin injection therapy is preferred to multiple daily injections as the latter may be too complex for them." (PMID 29508275, 2018).
diabetes (continued). "Thus, increases in IL‐6 level could be recognized in the kidney that was damaged to some extent by insulin‐resistant state or diabetes." (PMID 29632818, 2018). "Lack of UCN3 in turn might cause excessive insulin release, contributing to the pathophysiology of diabetes." (PMID 30400826, 2018). "SITA patients were more often female, more likely to have insulin treated diabetes (DM), DM with end organ damage, neurologic dysfunction and unstable angina." (PMID 30102699, 2018). "Majority of patients with diabetes mellitus (DM), who are on insulin therapy, use insulin pen for convenience, accuracy, and comfort." (PMID 29805817, 2018). "The CCI decrease in diabetes medication use was significantly greater than the changes in the UC group for all diabetes medications (P < 10−16) and all diabetes medications excluding metformin (P = 9.0 × 10−9), including sulfonylurea (P = 3.3 × 10−7) and insulin (P = 0.0002)." (PMID 29417495, 2018). "Thus, additional studies are needed to fully assess whether a pharmacological combination of insulin and glucagon could be beneficial in diabetes treatment." (PMID 29558502, 2018). "Insulin release by pancreatic β cells plays a key role in regulating blood glucose levels in humans, and to understand the mechanism for insulin secretion may reveal therapeutic strategies for diabetes." (PMID 29577067, 2018). "Diabetes management demands include frequent daily blood glucose monitoring, precise insulin calculations and adjustments, multiple insulin administrations via injections or subcutaneous insulin pump, and consideration of nutritional intake and physical activity." (PMID 29535081, 2018). "Both increased and decreased insulin secretion may be important in the development of diabetes." (PMID 30233498, 2018). "Both human and animal model networks presented in the current study point to relevant signals for the PI 3-kinase signaling pathway, which may be important for both insulin secretion and diabetes comorbidities originating in other tissues, such as cardiovascular disease." (PMID 29293525, 2018). "In insulin-naïve subjects included in the Swedish National Diabetes Register, the mean decrease in HbA1c over 12 months of treatment with basal insulin analogues was 7 ± 17 mmol/mol (0.6 ± 1.5%) for insulin glargine and 7 ± 18 mmol/mol (0.6 ± 1.6%) for insulin detemir." (PMID 29460260, 2018). "First, elevated glucose induces glycolytic genes in pancreatic beta cells, which induces a semi-stable persistent increase in insulin secretion, which could drive obesity and insulin resistance, and also due to glucose toxicity could eventually lead to beta-cell decompensation and diabetes." (PMID 29892261, 2018). "In Diabetes Mellitus (DM), normal physiological processes do not occur and chronic hyperglycaemia is observable, where glycaemic control is severely impaired because of prevailing deficiencies in insulin or its action." (PMID 29596514, 2018). "In addition, although our current model derives a ‘global’ rate of deterioration from diagnosis to insulin initiation, future developments may allow investigation of how the rate varies for therapies for diabetes and for other conditions." (PMID 29260253, 2018). "However, insulin therapy remains the most widely relied upon as the mainstay therapy for diabetes." (PMID 29508275, 2018). "There were more females as well as, non insulin-treated diabetes, diabetes with end organ damage (DM+EOD), EF ≤30%, Recent and Old MI, Left main disease, Emergency, Critical preoperative state,and preoperative use of IABP in the SITA group." (PMID 30102699, 2018). "Type 2 diabetes mellitus (DM) is a group of metabolic diseases; insulin resistance is a condition characterized by the failure to respond appropriately to insulin." (PMID 30064457, 2018).